ARL6 (ARF like GTPase 6)
Description:
Involved in membrane protein trafficking at the base of the ciliary organelle. Mediates recruitment onto plasma membrane of the BBSome complex which would constitute a coat complex required for sorting of specific membrane proteins to the primary cilia. Together with BBS1, is necessary for correct trafficking of PKD1 to primary cilia (By similarity). Together with the BBSome complex and LTZL1, controls SMO ciliary trafficking and contributes to the sonic hedgehog (SHH) pathway regulation. May regulate cilia assembly and disassembly and subsequent ciliary signaling events such as the Wnt signaling cascade. Isoform 2 may be required for proper retinal function and organization (By similarity).
Synonyms: BBS3; RP55
Tractability: Small molecule: a structure with a bound ligand is known. Antibody: its Gene Ontology location is reachable by antibodies, with high confidence; UniProt places it where antibodies can reach, with medium confidence. PROTAC: ubiquitination databases record sites on it; its protein half-life has been measured.
Gene: Protein-coding gene on chromosome 3 (97,764,521 to 97,801,229, forward strand). Ensembl gene ENSG00000113966.
Subcellular location: Cell projection, cilium membrane; Cytoplasm, cytoskeleton, cilium axoneme; Cytoplasm, cytoskeleton, cilium basal body
Subcellular location (Human Protein Atlas): Microtubules; Primary cilium; Cytosol; Nucleoplasm; Primary cilium tip
Pathways (Reactome):
Organelle biogenesis and maintenance: BBSome-mediated cargo-targeting to cilium
Gene Ontology:
Molecular function: protein binding; GTP binding; phospholipid binding; GTPase activity
Biological process: cilium assembly; protein localization to cilium; Wnt signaling pathway; determination of left/right symmetry; intracellular protein transport; melanosome transport; protein polymerization; protein targeting to membrane; fat cell differentiation; protein localization to non-motile cilium
Cellular component: ciliary tip; cilium; extracellular exosome; axonemal microtubule; axoneme; cytoplasm; membrane; membrane coat; plasma membrane; cytosol
Genetic constraint (gnomAD): Loss-of-function variants: 11 observed, 19.05 expected, observed/expected ratio (o/e) 0.58, 90% interval 0.36 to 0.96. The upper end of that interval is the gene's LOEUF score, 0.96, which puts it in group 4 of 6, group 1 being the genes least tolerant of losing a copy. Missense variants: 161 observed, 189.8 expected, observed/expected ratio (o/e) 0.85, 90% interval 0.75 to 0.97. Synonymous variants: 57 observed, 66.11 expected, observed/expected ratio (o/e) 0.86, 90% interval 0.7 to 1.08.
Gene-disease validity (ClinGen):
ClinGen rates the evidence that ARL6 causes each of these diseases.
ciliopathy (autosomal recessive): Definitive. A genetic disorder of the cellular cilia or the cilia anchoring structures, the basal bodies, or of ciliary function.
Homologues: Orthologues: pig ARL6 (98% identical), chimpanzee ARL6 (96% identical), mouse Arl6 (96% identical), guinea pig ARL6 (95% identical), rat Arl6 (95% identical), dog ARL6 (95% identical), rabbit ARL6 (94% identical), zebrafish arl6 (87% identical), tropical clawed frog arl6 (85% identical), Drosophila melanogaster Arl6 (54% identical), Caenorhabditis elegans arl-6 (43% identical). Paralogues in human: ARF3 (39% identical), ARF1 (38% identical), ARF4 (37% identical), ARL3 (37% identical), ARF6 (36% identical), TRIM23 (35% identical), ARF5 (35% identical), ARL13B (35% identical), ARL5B (34% identical), ARL5A (34% identical), ARL1 (33% identical), ARL2 (33% identical), and 18 more.
Diseases named in the same sentence as ARL6 in open-access papers:
ARL6 is named in the same sentence as 59 diseases in open-access papers, as found by Europe PMC text mining. Sharing a sentence is not in itself a finding about the gene and the disease. The quoted sentences say what the papers report.
Bardet-Biedl syndrome (20 papers, 2012 to 2025). A ciliopathy with multisystem involvement. "Autosomal recessive mutations in ARL3 or ARL13B cause Joubert Syndrome, while autosomal recessive mutations in ARL6 (also known as BBS3) lead to Bardet–Biedl Syndrome." (PMID 41446580, 2025). "Mutations in ARL6/BBS3 account for Bardet-Biedl syndrome-3 (OMIM #600151), which is characterized by retinal dystrophy, renal structural abnormalities, history of obesity, and skeletal abnormalities." (PMID 32850826, 2020). "ADP ribosylation factor like GTPase 6 (Arl6), also named as BBS3, is a member of the Ras superfamily of small GTPase, which is mutated in human Bardet–Biedl syndrome." (PMID 27999656, 2016). "The small GTPase Arl6 is implicated in the ciliopathic human genetic disorder Bardet–Biedl syndrome, acting at primary cilia in recruitment of the octomeric BBSome complex, which is required for specific trafficking events to and from the cilium in eukaryotes." (PMID 22609302, 2012). "Human Arl6 is encoded by Bbs3, one of 14 genes in which mutations are implicated in the autosomal recessive clinical disorder Bardet–Biedl syndrome (BBS)." (PMID 22609302, 2012). "Mutation of Arl6 causes Bardet-Biedl syndrome (BBS), a multisystemic disorder characterized by obesity, blindness, polydactyly, renal abnormalities, cognitive impairment and Hirschprung disease." (PMID 22427906, 2012). "The conventional retrieval pathway for activated GPCRs from the primary cilium back into the cytoplasm relies on the β-arrestin 2 and the BBSome, a complex of Bardet-Biedl Syndrome (BBS) proteins that forms a membranous coat in association with the Arf-like GTPase Arl6." (PMID 40610430, 2025). "ARL6 and CEP290 are 2 of the most frequently mutated genes in Bardet-Biedl syndrome, a multisystem primary ciliopathy characterized by heterogenous clinical manifestations, including cognitive impairment and developmental delay." (PMID 40924492, 2025). "In this vein, it is interesting to note that Arl6-mediated recruitment of Bardet-Biedl syndrome (BBS) protein can induce coated patches on liposomes, a process important for the primary ciliary entry." (PMID 25664179, 2015). "A mutation in the ARL6 Thr31 residue, which is important for GTP binding, was reported to cause Bardet-Biedl syndrome (BBS)." (PMID 22927989, 2012). "Arl6 is exclusively expressed in ciliated organisms, and its human ortholog ARL6, encoded by BBS3, was the first identified small GTPase protein that was linked to the human ciliopathy, Bardet-Biedl syndrome (BBS)." (PMID 23351793, 2012). "Bbs3 (Arl6) knockout mice display many of the characteristic features of Bardet–Biedl syndrome, including retinal degeneration and male infertility but also have unique phenotypes such as severe hydrocephalus, suggesting that the protein may have roles in addition to BBSome recruitment." (PMID 22609302, 2012).
ciliopathies (7 papers, 2012 to 2023). "Furthermore, the signature included genes whose mutations are known to cause ciliopathies with dysfunctions of primary cilia (e.g. ARL6, LCA5, TMEM67)." (PMID 22558177, 2012). "Mutations in some members of the ARL subfamily (e.g. ARL3, ARL6, ARL13B) are associated with ciliopathy diseases, emphasising that there is still a wealth of clinically relevant cellular mechanisms to undercover in the ARF family." (PMID 37622523, 2023). "The TES analysis of the 21 previously reported ciliopathy genes associated with BBS resulted in the identification of a novel synonymous variant c.534A > G; p.(Q178Q) in ARL6 in family F01, and a novel 11 bp deletion c.734_744del; p.(E245Gfs*18) in BBS5 in families F02 and F03." (PMID 27708425, 2016).
retinitis pigmentosa (6 papers, 2010 to 2022). Retinitis pigmentosa (RP) is an inherited retinal dystrophy leading to progressive loss of the photoreceptors and retinal pigment epithelium and resulting in blindness usually after several decades. "Patients from three families with a phenotype of EoHM and retinal dystrophy had variants in KCNV2 (OFT-00092), MERTK (OFT-00474) and ARL6 (OFT-00407), genes with a phenotype of retinal cone dystrophy in the case of KCNV2 and retinitis pigmentosa in the other two cases." (PMID 35457050, 2022). "NME3 could provide the substrate for cilium-associated G-proteins such as RPGR (retinitis pigmentosa), GPR48 (polycystic kidneys), RanGDP/GTP, and ARL6 (retinitis pigmentosa and BBS)." (PMID 30111592, 2018).
retinal degeneration (4 papers, 2012 to 2022). Degeneration of the retina. "In addition to pleiotropic disorder, there are also reports of non-syndromic retinal degeneration caused by mutations in the BBS genes BBS1, BBS2, ARL6/BBS3, and TTC8, disrupting the normal function of photoreceptor cilia." (PMID 32962042, 2020).
Retinal dystrophy (3 papers, 2020 to 2022). Retinal dystrophy is an abnormality of the retina associated with a hereditary process. "In the case of MERTK and ARL6 where EoHM was not reported, however, this manifestation might be a second consequence of the genetically determined retinal dystrophy." (PMID 35457050, 2022).
Conductive hearing impairment (1 paper, 2020). An abnormality of vibrational conductance of sound to the inner ear leading to impairment of sensory perception of sound. "Arl6 has been linked to both sensorineural and conductive hearing impairment, while Pou1f1 is associated with the abnormal orientation of outer hair cell stereociliary bundles, and abnormal morphology in outer hair cells, stria vascularis, and the tectorial membrane in the cochlea." (PMID 32587610, 2020).
hepatocellular carcinoma (1 paper, 2024). A malignant tumor that arises from hepatocytes. "Additionally, we examined ARL-6 expression in hepatocellular carcinoma of the liver with various clinical features using the UALCAN database." (PMID 38169538, 2024).
liver cancer (1 paper, 2024). An epithelial or non-epithelial malignant neoplasm that arises from the liver. "Western blotting revealed the expression of ARL-6 in human liver cancer cell lines (Hep-G2, Hep3B, Alexander, Huh7, SMMC7721, and MHCC97-L), as well as in a human normal liver cell line (LO2)." (PMID 38169538, 2024). "Furthermore, according to GEPIA data, the expression levels of ARL-6 were significantly increased in liver cancer tissue compared to healthy liver tissue." (PMID 38169538, 2024).
retinal disease (1 paper, 2025). "A majority of the significantly differentially expressed (FC > 2, FDR < 1%) genes show an increase in expression with higher glucose; these include genes involved in retina development (Neurod1, Casz1, and Crxos) or those associated with retinal disease (Impg1/2, Gucy2f, Mpp4, Arl6, and Rp1)." (PMID 40568109, 2025).
retinitis punctata albescens (1 paper, 2022). "The purpose of this study was to determine the ocular characteristics of a boy with BBS caused by a novel homozygous variant in the ARL6 (alternative named BBS3) gene who had been originally diagnosed with retinitis punctata albescens." (PMID 36550847, 2022).
cancer (2 papers, 2017 to 2024). A tumor composed of atypical neoplastic, often pleomorphic cells that invade other tissues. "Although ARF family members have been implicated in tumor development through their influence on cancer cell proliferation, migration, and invasion 8, 11-15, the role of ARL-6 in HCC remains largely unclear." (PMID 38169538, 2024). "Immunohistochemistry further revealed that ARL-6 expression was remarkably higher in HCC than in para-carcinoma tissues." (PMID 38169538, 2024). "The ARF-like family of proteins, including ARL-6, exhibits diverse roles in various cancer types." (PMID 38169538, 2024). "The involvement of ARL-6 in HCC development and its influence on immune cell infiltration make it a promising candidate for targeted cancer therapies." (PMID 38169538, 2024). "Nevertheless, the expression of ARL-6 and its role within the ARF-like family in other types of cancer warrants further exploration." (PMID 38169538, 2024). "In conclusion, our results suggest that the ARL-6 gene may play a role in controlling tumor growth and may have immunotherapeutic implications for HCC by impacting tumor prognosis and the cancer immune microenvironment." (PMID 38169538, 2024).
infection (2 papers, 2009 to 2012). The state of being infected such as from the introduction of a foreign agent such as serum, vaccine, antigenic substance or organism. "Parasite concentrations in the blood were greater than 5 × 107/ml in mice infected with either the parental or RNAi line by 72 h, indicating that parasites with a modest reduction in ARL6 due to RNAi retain the ability to mount an infection in vivo." (PMID 22609302, 2012).
tumor (2 papers, 2016 to 2024). "Using the GEPIA database, we assessed the relationship between differentially expressed ARL-6 and the tumor grade of HCC cases to determine the association of ARL-6 with HCC prognosis, progression, and carcinogenesis." (PMID 38169538, 2024). "A significant correlation (P=0.0459) was observed between ARL-6 expression and tumor grade, with the highest expression of ARL-6 found in grade III tumors." (PMID 38169538, 2024). "The investigation into ARL-6 gene expression in tumor tissues was conducted using the TIMER database." (PMID 38169538, 2024). "To further characterize the tumor suppression properties of Arl6 knockdown, we examined the ability of RH30 cells to undergo apoptosis when stably expressing shArl6." (PMID 27999656, 2016). "More research is needed to develop the compounds inhibiting the expression or GTP-binding of Arl6 for tumor therapy." (PMID 27999656, 2016). "However, there is still a knowledge gap regarding the precise function of ARL-6 in the tumor immune microenvironment that requires further investigation." (PMID 38169538, 2024). "Furthermore, our study indicated positive correlations between ARL-6 expression levels and the activities of tumor-infiltrating immune cells such as B cells, myeloid dendritic cells, macrophages, neutrophils, CD8+T cells, and CD4+T cells." (PMID 38169538, 2024). "ARL6-siRNA treated Huh7 cells demonstrated an obvious impact of ARL6 on tumor invasion compared to the negative control groups (P<0.001)." (PMID 38169538, 2024). "Thus, our study delves into the expression and functions of ARL-6 in the context of HCC, aiming to elucidate its potential to impact prognosis by regulating the biological activity of HCC tumor cells." (PMID 38169538, 2024). "However, the differential expression level of ARL-6 combined with the tumor grade of HCC patients did not have a statistically significant effect on HCC prognosis." (PMID 38169538, 2024).
ARL6 also shares sentences with these, for which no sentence is quoted: Obesity (5 papers); cone-rod dystrophy (3); Hydrocephalus (3); Usher syndrome (3); Alström syndrome (2); myopia (2); Arts syndrome (1); bladder urothelial carcinoma (1); Blindness (1); breast invasive carcinoma (1); cholangiocarcinoma (1); Cognitive impairment (1); colitis (1); colon adenocarcinoma (1); cone dystrophy (1); congenital diaphragmatic hernia (1); developmental and epileptic encephalopathy (1); developmental delay (1); Duane retraction syndrome (1); Dyskinesia (1); esophageal carcinoma (1); genetic disorder (1); Glucose intolerance (1); head and neck cancer (1); hyperlipidemia (1); Insulin resistance (1); Joubert syndrome (1); kidney chromophobe (1); lung adenocarcinoma (1); lung squamous cell carcinoma (1).
A further 16 diseases each share a sentence with ARL6 in 1 paper.